ANXA1 (annexin A1)
Diseases named in the same sentence as ANXA1 in open-access papers (continued):
Sharing a sentence is not in itself a finding about the gene and the disease.
cancer (continued). "Molecular docking data and physicochemical analysis suggested that PL shows potential interactions with a peptide of annexin A1 (ANXA1), an endogenous anti-inflammatory mediator with therapeutic potential in cancer." (PMID 33335138, 2020). "As stated in Section 2.2.2, ANXA1 can be incorporated in PCC-derived EVs and modulate the motility of cancer cells." (PMID 32756339, 2020). "DCST1-AS1 has been found to bind to annexin A1 directly in triple-negative breast cancer (TNBC) cells to modulate the transcription of its downstream regulatory genes involved in EMT and cancer drug resistance." (PMID 33114183, 2020). "DC-STAMP domain-containing 1-antisense 1 (DCST1-AS1) and annexin A1 are two genes functioning downstream of TGF-β that play key roles in EMT and cancer chemotherapy resistance." (PMID 33114183, 2020). "High ANXA1 expression exerts its effect via inhibition of CC and CXC subfamily members, leading to a restricted in immune response to cancers." (PMID 32226026, 2020). "The miR-221-3p targets genes at early stage such as Annexin A1 (ANXA1), Cyclin Dependent Kinase Inhibitor 1B (CDKN1B), and multiple genes during advance-stage cancer such as CDKN1B, PTEN, Ring Finger Protein 20 (RNF20), Estrogen Receptor 1 (ESR1) and AKT3." (PMID 31756185, 2019). "Here, ANXA1 released from the apoptotic cells can bind to formyl peptide receptor 1 receptor on APCs, enabling the stable interaction between the APC and dying cancer cell." (PMID 29666625, 2018). "Subpopulation B consisted of 121 cells (29.1%) and showed overexpression of 13 genes, including seven cancer genes (HSPB1, ANXA1, SLPI, KRT8, KRT19, KLK7, and ABL2) and several Keratin genes (KRT8, KRT7, KRT19, and KRT6B)." (PMID 28794488, 2017). "qPCR analysis of a number of reported miR196a targets in other cancers, KRT5, ANXA1, S100A9 and HOXC8, was conducted." (PMID 25860510, 2015). "Exogenous overexpression of ANXA1 significantly impaired the colony formation and migration of AGS and N87 cancer cells." (PMID 25038797, 2014). "Proliferation analysis showed that full-length ANXA1-transfection leads to proliferation arrest of AGS and N87 cancer cells." (PMID 25038797, 2014). "Here we showed a huge increase of CCK mRNA expression in tumors from annexin A1 ko mice, the further study of interaction of annexin A1 and CCK will shed light on understanding the role of CCK in human cancers." (PMID 23077482, 2012). "While EGFR signaling is a central target in metastatic CRC therapy, ANXA1 may enhance both EGFR activation and stabilization, thereby contributing to cancer immune evasion via the ANXA1/EGFR interaction." (PMID 41283264, 2025). "A suppression of CD8+ cytotoxic T cells and an expansion of the Tregs population may also be induced by ANXA1 overexpression in TME by FPR2/STAT3 signaling activation, contributing to therapy resistance in several cancer types, including CRC." (PMID 41283264, 2025). "In this current study, several CAFGs—VIM, ANXA1, HOPX, CALD1, and COL8A1—were confirmed highly expressed in TC cells, but not in those of other cancers (except ANXA1 in PDAC)." (PMID 41228323, 2025). "Cancers tend to get rid of substances like ANXA1 through down regulation so its development is not intercepted." (PMID 38892394, 2024). "Since ST data has not yet reached single-cell resolution, ANXA1 also exhibited strong expression in myeloid and mesenchymal spots of cancers and elevated in advanced stages." (PMID 38645221, 2024). "However, due to its contradictory activity in cancer in general and in LSCC, further research is needed in order to determine the clinical meaningfulness of ANXA1." (PMID 38893148, 2024). "Significantly higher PS externalization was detected in m/lEVs (annexin A1+) derived from cancer cells compared to m/lEVs (annexin A1+) from non-cancerous cells." (PMID 36992223, 2023).
cancer (continued). "Several glucocorticoid-inducible proteins play important roles in pathogenesis of some cancers but their status and roles in HPV-OPSCC remain elusive; these include the glucocorticoid-induced leucine zipper (GILZ), Annexin-A1 and serum glucocorticoid-regulated kinase-1 (SGK-1)." (PMID 37954869, 2023). "In the single EV assay, we detected more PS-exposing m/lEVs from both cancer cell lines than non-cancerous cells by dual-labeling m/lEVs with anti-annexin A1 antibodies and PS-binding proteins." (PMID 36992223, 2023). "However, cumulative evidence shows that ANXA1 acts as an upstream regulator of the PI3K pathway in several normal and cancer cell models." (PMID 36631478, 2023). "In addition, interaction between actively or passively released annexin A1 (ANXA1) and formyl peptide receptor 1 (FPR1) also contributes to anti-cancer immune responses to chemotherapy." (PMID 37153795, 2023). "Similar to in vivo regulatory effects of ANXA1 peptides, ANXA7 protein segments could have therapeutic potential in cancer or other pathologies that involve PS membrane dynamics with phospholipid-associated signaling and metabolism." (PMID 37240163, 2023). "GlaS showed the same tendency as annexin A5 and slightly higher signals in cancer cell-derived m/lEVs (annexin A1+) but was not statistically significant." (PMID 36992223, 2023). "Concretely, ANXA1 appeared to be overexpressed in the carcinoma tissues but not in the para-carcinoma tissues." (PMID 36678567, 2023). "DAMPs released during ICD comprise chaperones of endoplasmic reticulum (ER) such as heat-shock proteins (HSPs) and calreticulin (CALR), type I interferons (I-IFNs), non-histone chromatin-binding protein HMGB1, ATP, annexin A1 (ANXA1), and cancer cell-derived nucleic acids." (PMID 35488303, 2022). "The interaction between ANXA1 and FPR1 has been suggested to result in anti‐inflammatory processes in diseases such as cancer, where interactions of these two proteins on murine dendritic cells (DCs) were shown to establish DC/corpse synapses and clearance of dead cells." (PMID 35146757, 2022). "Since ANXA1 expression is closely related to inflammatory processes, the signaling axis ANXA1/FPR could constitute an attractive immunomodulatory target for cancer therapies." (PMID 36247003, 2022). "Upon apoptosis induction, however, we detected minute amounts of Annexin A1 in supernatants of the cancer cell line HCT 15 only (data not shown)." (PMID 36123610, 2022). "ANXA1 dysregulation has been frequently detected in many types of cancer; however, its specific role has not yet been fully deciphered." (PMID 36247003, 2022). "Additionally, ESCC biomarkers identified in previous study, such as ACTA2, ANXA1, HSPA9, THBS1 etc. were also detected in EESCC, indicating the key events in advanced-stage cancer happened as earlier as in the early-stage cancer." (PMID 35397555, 2022). "Similar to inflammatory disease, there is a large amount of literature suggesting a role for ANXA1 in cancer, but this role has not been well defined." (PMID 35146757, 2022). "The interaction between ANXA1 and FPR1 was suggested to influence intratumoral DC maturation and T cell‐mediated anticancer immune responses, thus abolishing the efficacy of anthracycline‐based chemotherapy in cancer." (PMID 35770335, 2022). "ANXA1 acts as an extracellular similar to the formyl peptide receptor (FPR) ligand or cytoskeleton remodeling factor and promotes the migration and invasion of cancer cells." (PMID 34439260, 2021). "Although ANXA1 was initially found to inhibit the inflammatory response, that has not been shown in cancer models." (PMID 33804148, 2021). "Here, we will discuss how Annexin A1 in cancer does not inhibit PLA2 leading to both pro-inflammatory and pro-tumoral signaling pathways." (PMID 34208346, 2021).
cancer (continued). "It is well established that some annexins, including ANXA1 and ANXA2, can be secreted out of the cell through unconventional secretory mechanisms, with implications in many functions such as the endocrine regulation, inflammatory response and cancer." (PMID 31940782, 2020). "There are independent reports on increased expression levels or increased autoantibodies for ANXA1 in several cancers, however, there is no report on a correlation between increased expression levels and autoantibody levels." (PMID 33261560, 2020). "Annexin A1 has been extensively investigated as an anti-inflammatory protein, but its role in different types of cancer has not been consolidated in a single systematic review to date." (PMID 32823805, 2020). "We found that ANXA1 high tumors enriched inflammation and EMT gene sets, which suggest that previously reported mechanisms using in vitro and in vivo experiments are in place in human cancer and are clinically relevant." (PMID 31461932, 2019). "ANXA1 positivity in cancer cells had no statistical relationship with the clinical characteristics of the patients." (PMID 31461932, 2019). "Although the literature highlights the role of CatD and cleaved AnxA1 in cancer, there are no studies correlating both in BC." (PMID 30884823, 2019). "Since cleaved AnxA1 is highly expressed in MDA-MB-231 and required for the growth and survival of cancer cells, in this investigation we hypothesized that CatD may prevent apoptosis in TNBC." (PMID 30884823, 2019). "For example, miR-21, miR-125b, miR-181a, miR-196a, and miR-148b suppress the expression of the apoptosis-related genes caspase-3, intercellular adhesion molecule-2 (ICAM-2), Protein Kinase C Delta (PRKCD), annexin A1 (ANXA1), or DNA methyltransferase 3b (DNMT3B) in a wide spectrum of cancers." (PMID 31174564, 2019). "The determination of the cell fate by ANXA1 was dependent on the subcellular protein localization not only in cancer cells but also in neural cells." (PMID 30364320, 2018). "On the other hand, miR-34c, miR-455, miR-202, miR-137, which are upregulated in absence of ANXA1, exert cancer suppression." (PMID 29986379, 2018). "Several biochemical approaches have revealed the importance of the cleavage for the ANXA1 functions in the inflammatory system, not yet in cancer models." (PMID 30518142, 2018). "In addition to cancer progression, ANX family proteins (ANXA1 and ANXA2) suppress the efficacy of both chemotherapy and radiotherapy." (PMID 29598816, 2018). "Our study provides evidence that ANXA1 modulates TAM function and phenotype through FPR2-ERK signalling, involving CCL5 in the microenvironment, suggesting a potential new axis for targeting cancer therapy." (PMID 29263330, 2017). "Cancer cell migration was assessed using a wound healing assay, which revealed a decreased migration capacity in siRNA-Annexin A1 transfected AGS cells compared to controls, but increased migration in cells transfected with a plasmid overexpressing Annexin A1." (PMID 27941907, 2016). "The molecular pathway of gene ANXA1 in the modulation of carcinogenesis is related to its action as a substrate to the epidermal growth factor receptor (EGFR) and protein kinase C (PKC), which implies its involvement in signal transduction pathways to cancer." (PMID 24719523, 2014). "Thus, we further aimed to compare the binding efficiencies of annexin A5 and GlaS proteins to PS-exposing sEVs and m/lEVs, identified by CD63 or annexin A1 positivity, respectively, derived from cancer and non-cancerous cells using single EV flow cytometry." (PMID 36992223, 2023). "Indeed, miR-196 may play a critical role in cancer pathogenesis by targeting several regulation molecules including HOXB8, HMGA2, and annexin A1." (PMID 35563269, 2022). "Nonetheless, it is suggested that Annexin A1 may serve as a partial functional mediator of tumorigenesis and metastasis rather than a tissue-specific mediator for predicting cancer initiation and/or metastasis." (PMID 34943928, 2021).
cancer (continued). "Therefore, the direct inhibition of PLA2 or the inhibition of AnxA1 cleavage, with the subsequent resumed anti-PLA2 activity, could represent interesting therapeutic strategies in the cancer context." (PMID 34208346, 2021). "Moreover, it is known that AnxA1 regulates the nuclear localization of EGFR and, as a consequence, it can promote immune evasion by favoring the EGFR/STAT3 transcriptional activities in cancer cells." (PMID 34571894, 2021). "We hypothesize an OOC scenario in which DAC induces cancer cells to undergo apoptosis, with a concomitant release of apoptosis-dependent chemokines or via the activation of pathways strictly related to cell death such as the FPR1/Anxa1 axis." (PMID 33842539, 2021). "It has been suggested that in vitro nuclear translocation of ANXA1 could be induced by mitogenic signals and that it could be a negative prognostic factor in cancer." (PMID 27655189, 2016). "The inhibition of ANXA1 expression by miR196a is not novel as other groups have described that ANXA1 may be lost in cancer due to inhibition by miR196a." (PMID 27105503, 2016). "Although the precise mechanism of Annexin A1 in cancer development and progression is still not clearly understood, more emphasis has been placed on this protein in the field of carcinogenesis, cancer diagnosis and cancer treatment." (PMID 23786757, 2013). "Annexin A1 and TGFBI could be important therapy targets to manipulate to improve the efficacy of radio-and chemo-therapies for cancer patients, to reduce resistance to treatments and decrease recurrence of cancer." (PMID 23077482, 2012). "Additionally, by IHC the endothelial cells lining the vasculature in the microenvironment in cancer stained positive for annexin A1 but absent staining was noted in the controls." (PMID 18637184, 2008). "Furthermore, ANXA1 downregulates the expression of cyclooxygenase-2 (COX-2), leading to suppressed prostaglandin synthesis and reduced inducible nitric oxide synthase (iNOS) levels, reinforcing its anti-inflammatory role, with a significant contribution to cancer progression modulation." (PMID 41283264, 2025). "High annexin A1, low stress, and high mTOR-S6 signaling might seem contradictory in TNBC but there are several molecules that play distinctive roles in different stages of development and cancer and it is the overall effect of these alterations that determines the outcome of the process." (PMID 26000884, 2015). "However, the impact of RRM2 on the sensitivity of PCA to docetaxel treatment is not yet clear.Annexin A1 (ANXA1) is a calcium dependent phospholipid binding protein closely related to various cellular activities, such as inflammation and apoptosis, as well as cancer cell proliferation." (PMID 37968699, 2023).
infection (47 papers, 2008 to 2026). The state of being infected such as from the introduction of a foreign agent such as serum, vaccine, antigenic substance or organism. "This pronounced variance between co-inoculated wildtype and knockout mice was sustained over most of the course of infection, raising additional questions surrounding the effect of ANXA1 deficiency on the adaptive immune response." (PMID 39076982, 2024). "Analysis of the infection rate of myeloid cells derived from wildtype or ANXA1-deficient mice by L. major indicated a significant LeishEXO-dependent increase in infectivity." (PMID 39076982, 2024). "Overall, these data indicate that ANXA1 deficiency significantly abrogates myeloid cell infection by L. major, which is typically exacerbated by the presence of LeishEXO in wildtype animals." (PMID 39076982, 2024). "In this study, we evaluated the roles of AnxA1 and Fpr2 in a mouse model of S. suis meningitis created via intracisternal infection in Fpr2-deficient (Fpr2−/−) and wild-type (WT) mice." (PMID 33318141, 2021). "Lung inflammatory injury is exacerbated in AnxA1-deficient mice in several in vivo models of lung inflammation and infection, suggesting that this proresolving mediator has a general protective role in the lung." (PMID 31398292, 2019). "The release of ANXA1 in the epithelial lining during peak infection could prevent the adverse effects caused by NE by inducing mucosal restoration and clearance of inflammation." (PMID 37630454, 2023). "We observed that CL patients exhibit significantly higher levels of both ANXA1 and IL-1β in serum when compared to HS, reinforcing the hypothesis that ANXA1 may play an important role in modulating the systemic inflammatory response associated with infection." (PMID 41200163, 2025). "In this study, we have shown that endogenous AnxA1 protects mice from excessive neutrophilic infiltration and lung inflammation/damage during infection with a murine betacoronavirus." (PMID 40956847, 2025). "Of note, AnxA1 is one of the most studied pro-resolving mediators and holds significant impact in the course of infections." (PMID 40956847, 2025). "Here, using genetically ablated mice for AnxA1 and different coronaviruses, we demonstrated that endogenous AnxA1 expression increases during infection and that the molecule undergoes cleavage during this process." (PMID 40956847, 2025). "In this study, we described the histopathological processat the lesion site, the presence of cytokines, and ANXA1 during infection withL." (PMID 39082522, 2024). "An in vitro study of the effect of FPR agonism on myeloid cell infection by L. major was then performed using peritoneal macrophages isolated from both wildtype and ANXA1-/- mice." (PMID 39076982, 2024). "Specifically, ANXA1 interacts with FPRs to enhance the recruitment and infection of myeloid cells, leading to increased early infection rates that persist over time and severe cutaneous lesions." (PMID 39076982, 2024). "To study this, we utilized in vivo, ex vivo, and in vitro studies to provide evidence that leishmanial exosomes exploit the ANXA1/FPR axis to enhance myeloid cell invasion by Leishmania in the early stages of infection, driving immunopathogenesis." (PMID 39076982, 2024). "ANXA1 showed protective activity against Toxoplasma gondii infection, based on the observation that the third-trimester placentas expressing lesser ANXA1 were more permissive to this infection than the first-trimester placentas expressing more ANXA1." (PMID 37373303, 2023). "It was demonstrated that AnxA1 levels were decreased in the gut, and increased systemically during early infection of SIV in rhesus macaques." (PMID 37190040, 2023). "The levels of these factors were shown to be positively correlated with the severity of infection; our results demonstrate that serum AnxA1 level can be used to evaluate the severity of CAP." (PMID 36766501, 2023).